CXCL14 (C-X-C motif chemokine ligand 14)
Diseases named in the same sentence as CXCL14 in open-access papers (continued):
Sharing a sentence is not in itself a finding about the gene and the disease.
cervical cancer (5 papers, 2021 to 2025). A primary or metastatic malignant neoplasm involving the cervix. "Since the promoter of the CXCL14 gene contains HRE, chronic hypoxia can increase the expression of CXCL14, for example, in cervical cancer cells." (PMID 33467722, 2021). "Literature evidence supports their biological relevance: CXCL14 is silenced via HPV E7-induced promoter hypermethylation, impairing immune recognition, while MTUS1 functions as a tumor suppressor and is downregulated in invasive cervical cancer." (PMID 40951335, 2025).
liver cancer (5 papers, 2016 to 2026). An epithelial or non-epithelial malignant neoplasm that arises from the liver. "This study also found that the CXCL14 protein inhibited the growth activity and migration ability of liver cancer cells to a certain extent, which is similar to that reported by others in liver cancer." (PMID 37835641, 2023). "Overexpression of CXCL14 has shown antitumor effects by suppressing tumor growth and cancer cell migration in breast, oral, lung, and liver cancers (17, –, 19, 38, 39)." (PMID 27143385, 2016).
liver fibrosis (5 papers, 2021 to 2025). "Similarly, Jak2 overexpression mitigated the effects of CXCL14 deficiency in a BDL‐induced liver fibrosis model." (PMID 39358917, 2024). "Moreover, Jak2 overexpression reversed the inhibition of liver fibrosis caused by CXCL14 knockdown in vivo." (PMID 39358917, 2024). "The chemokine CXCL14 is also involved in the ATF3/Cxcl14/Jak2 signaling axis in hepatic stellate cells responsible for liver fibrosis." (PMID 40893164, 2025). "In conclusion, our results provide strong evidence supporting the critical role of CXCL14 in driving the transformation of HSCs into myofibroblasts and the progression of liver fibrosis." (PMID 39358917, 2024). "Findings revealed that the specific deletion of CXCL14 in HSCs suppressed liver fibrosis in mice via the activating transcription factor 3 (ATF3)/CXCL14/RUNX1/JAK2 signalling pathway." (PMID 39358917, 2024). "This increase correlated with fibrosis markers, suggesting a potential role for CXCL14 in the pathogenesis of liver fibrosis and cirrhosis." (PMID 39358917, 2024). "This study aimed to investigate the function of CXC motif ligand 14 (CXCL14) in the progression of liver fibrosis." (PMID 39358917, 2024). "This study reveals a regulatory mechanism involving CXCL14, where the use of antagonists or blocking antibodies against CXCL14 led to a significant reduction in liver fibrosis in established animal models." (PMID 39358917, 2024). "The attenuation of liver fibrosis in CXCL14−/− cKd mice suggests that CXCL14's profibrogenic effects are primarily mediated through its intrinsic action on HSCs." (PMID 39358917, 2024). "Consistent findings were observed in the BDL model, where α‐CXCL14 treatment improved liver injury, reduced hepatic immune infiltration, and alleviated liver fibrosis." (PMID 39358917, 2024). "Collectively, these results suggest that inhibiting CXCL14 plays a key role in mitigating liver fibrosis." (PMID 39358917, 2024). "This study aimed to investigate the role of CXCL14 in liver fibrosis." (PMID 39358917, 2024). "Given the predominant expression of CXCL14 in HSCs during liver fibrosis, this study aimed to determine whether selectively depleting CXCL14 in HSCs could alleviate liver fibrosis." (PMID 39358917, 2024). "CXCL14 knockdown significantly reduced the extent of liver fibrosis." (PMID 39358917, 2024). "Consequently, CXCL14 was identified as a novel regulator of liver fibrosis with potential therapeutic applications." (PMID 39358917, 2024). "Moreover, targeting the CXCL14‐Jak2 signalling axis presents a promising therapeutic avenue for the treatment of liver fibrosis." (PMID 39358917, 2024). "The role of CXCL14 interference in the suppression of liver fibrosis was investigated." (PMID 39358917, 2024). "However, much of the previous research has focused on the upstream mechanisms of CXCL14 in liver fibrosis, leaving its downstream effects and potential clinical applications less explored." (PMID 39358917, 2024). "However, Jak2 overexpression reversed the suppression of liver fibrosis due to CXCL14 knockdown, as evidenced by hyp quantification, Masson, and Sirius red staining." (PMID 39358917, 2024). "Interestingly, Cxcl14 is highly expressed in experimental liver fibrosis with different etiologies, such as bile duct ligation, carbon tetrachloride or ethanol, and neutralization of CXCL14 was found to reduce carbon tetrachloride induced liver injury and steatosis in mice." (PMID 34835949, 2021). "In summary, these results indicate that CXCL14 facilitates HSC activation and liver fibrosis through the Jak2 pathway." (PMID 39358917, 2024). "To further elucidate the functional relationship between CXCL14 and Jak2, we investigated whether CXCL14 promotes HSC activation and liver fibrosis through Jak2." (PMID 39358917, 2024). "Notably, both global CXCL14 deletion (CXCL14−/−) and HSC/myofibroblast‐specific CXCL14 knockdown significantly attenuated liver fibrosis in mice." (PMID 39358917, 2024).
liver fibrosis (continued). "Our results demonstrate that CXCL14 is specifically upregulated in HSCs during liver fibrosis, with no corresponding induction in hepatic parenchymal cells." (PMID 39358917, 2024). "In reduction of CXCL14 mice, liver fibrosis was notably suppressed without impacting liver injury markers (ALT/AST) or immune infiltration in both CCl4 and BDL models." (PMID 39358917, 2024). "CXCL14 is a recently discovered member of the CXC chemokine family, whose overexpression remarkably aggravates CCl4-induced liver injury, making it a potential therapeutic target for liver fibrosis." (PMID 36059967, 2022).
psoriasis (5 papers, 2013 to 2025). An autoimmune condition characterized by red, well-delineated plaques with silvery scales that are usually on the extensor surfaces and scalp. "Furthermore, CXCL14, previously associated with anti-inflammatory effects in psoriasis, was also highly expressed in this cluster, in contrast to its overall decrease in psoriatic lesions." (PMID 40537825, 2025). "Both CXCR4 and CXCL14 show significantly elevated expression in all psoriasis-related conditions compared to normal skin." (PMID 40351602, 2025). "The identification of CXCL14 + proliferating keratinocytes in psoriasis exemplifies scExtract’s capability to uncover previously understudied cellular dynamics in complex diseases." (PMID 40537825, 2025). "While CXCL14-mediated MC activation and chemotaxis may contribute to idiopathic lung fibrosis with an excess of the chemokine, our findings suggest that the SP-MRGPRX2 pathway plays a crucial role in inflammatory skin conditions, neurogenic inflammation, including itch, psoriasis, and urticaria." (PMID 39435146, 2024).
pulmonary fibrosis (5 papers, 2018 to 2025). Chronic progressive interstitial lung disorder characterized by the replacement of the lung tissue by connective tissue, leading to progressive dyspnea, respiratory failure, or right heart failure. "Multiple studies have shown that chemokines such as CXCL9, CXCL10, and CXCL11 promote pulmonary fibrosis by recruiting fibrosis-related macrophages, but the role of CXCL14 in IPF has long been overlooked." (PMID 40842541, 2025). "In conclusion, we discovered MRGPRX2 as a target of the orphan proinflammatory chemokine CXCL14 both of which are upregulated in pulmonary fibrosis." (PMID 38184723, 2024). "Patients with idiopathic pulmonary fibrosis show a strongly upregulated expression of chemokine CXCL14, whose target is still unknown." (PMID 38184723, 2024). "This study reveals that the proinflammatory chemokine CXCL14 activates MAS-related G protein-coupled receptor MRGPRX2; these results provide a rational basis for the future development of idiopathic pulmonary fibrosis therapies." (PMID 38184723, 2024). "Furthermore, it had been published that the CXCL14/CXCR4 chemokine axis is involved in the progression and/or activation of fibroblasts during initiation of pulmonary fibrosis in the lung." (PMID 33670189, 2021).
Sepsis (5 papers, 2016 to 2025). Sepsis is defined as life-threatening organ dysfunction caused by a dysregulated host response to infection. "Together, these results suggest that CXCL14 overexpression attenuates sepsis-associated AKI probably through the downregulation of macrophages-derived cytokine production." (PMID 32317861, 2020). "Together, these findings first demonstrated CXCL14 overexpression attenuate sepsis-associated AKI probably through the modulation of M1/M2 polarization." (PMID 32317861, 2020). "Notably, CXCL14 has been reported to inhibit M1 macrophage polarization and proinflammatory cytokine production in a sepsis-associated kidney injury model." (PMID 37904257, 2023). "In addition, the expression of M2 marker Arg-1 in injured kidneys was significantly increased in the CXCL14 − Tg + CLP group even in the early stage of sepsis-associated AKI as compared with the CLP group (p < 0.001, respectively)." (PMID 32317861, 2020). "In the present study, we aim to test the hypothesis that CXCL14 protects animals against sepsis-associated AKI and improves survival outcome of septic animals." (PMID 32317861, 2020). "The present study was designed to investigate whether CXCL14 overexpression attenuates sepsis-associated acute kidney injury (AKI) in mice." (PMID 32317861, 2020). "In the past decades, a lot of research has been done to study CXCL14-mediated effects in cancers; however, few evidences regarding its effects in sepsis or septic shock have been reported." (PMID 32317861, 2020). "CXCL14 was abundantly expressed in the liver following CLP‐induced sepsis." (PMID 39444093, 2025). "CXCL14 has been detected in kidney specimens, however, it has not been extensively investigated, except for a study where CXCL14 overexpression mitigates sepsis-induced AKI, probably through the regulation of the M1/M2 macrophage ratio and the downregulation of cytokine production." (PMID 35806457, 2022).
Lewis lung carcinoma (4 papers, 2012 to 2025).
oral cavity squamous cell carcinoma (4 papers, 2016 to 2025). A squamous cell carcinoma arising from the oral cavity. "CXCL14 also promotes tumor lymphocyte infiltration in oral squamous cell carcinoma." (PMID 38714539, 2024). "Notably, CXCL14, which is downregulated in NASH-HCC, has been shown to be positively associated with the TIL pathway, suggesting its potential role in promoting immune cell infiltration within the tumor microenvironment of oral cavity squamous cell carcinoma." (PMID 40881277, 2025).
steatosis (4 papers, 2013 to 2023). Increased lipid within the cytoplasm of cells. "Second, we observed that targeting CXCL14 appeared to attenuate both neutrophil infiltration and steatosis in mice." (PMID 36722664, 2023). "Their findings indicate that the main effect of Cxcl14 neutralisation in the liver is prevention of necrosis and steatosis following an injury." (PMID 28775895, 2017). "Therefore, it is reasonable to speculate that CXCL14 contributes to steatosis by virtue of promoting neutrophil infiltration." (PMID 36722664, 2023). "In patients with advanced hepatic steatosis (score ≥ 3), chemokine (C-X-C motif) ligand 14 (CXCL14), interleukin-1 family member 10 (IL1F10), and interleukin 8 receptor β (IL8RB) had a significant differential expression (P ≤ 0.05) as compared to those with mild steatosis (score ≤ 2)." (PMID 23661906, 2013).
viral infection (4 papers, 2020 to 2024). "CXCL14 (chemokine (C-X-C motif) ligand 14) primarily contributes to immune cell migration and antibacterial immunity, which is crucial in the host defense against viral infections by enhancing the innate immune response." (PMID 38397195, 2024). "In addition, levels of chemokines CXCL2, CXCL8, CXCL20 and CXCL14 were higher in men, which supports the hypothesis that the first stage of male response against a viral infection is typically related to inflammation and Th17 cell differentiation processes." (PMID 33271804, 2020). "Notably, we discovered upregulation of multiple ISGs, such as ZBTB16, MX1, OASL, RSAD2, CMPK2, and CXCL14 in the DiMNF treated primary cells, even in the absence of viral infection." (PMID 37672505, 2023).
Alzheimer disease (3 papers, 2022 to 2025). A progressive, neurodegenerative disease characterized by loss of function and death of nerve cells in several areas of the brain leading to loss of cognitive function such as memory and language. "Taking the critical role of microglia polarization in Alzheimer’s disease into consideration, whether Ehmt2/H3K9me2/CXCL14 axis is also involved in the pathology of other neurological disorders should be discussed in the future study." (PMID 36064768, 2022). "CXCL14 (C-X-C motif chemokine ligand 14) is a chemokine involved in immune system regulation and inflammation, and emerging research suggests it may play a role in Alzheimer’s disease." (PMID 40341634, 2025).
bladder cancer (3 papers, 2022 to 2025). "Western blot analysis revealed that exogenous CXCL14 significantly increased ERCC4 expression in bladder cancer cells in CXCL14-deficient CAFs." (PMID 40898244, 2025). "Therefore, we next examined whether deficient expression of CXCL14 in CAFs affects cisplatin induced DNA damage in bladder cancer cells." (PMID 40898244, 2025). "Cell viability assays indicated that CAF/CM-induced chemoresistance to cisplatin in bladder cancer cells was significantly blocked after CXCL14 was intervened in CAFs." (PMID 40898244, 2025). "In conclusion, we elucidated a mechanism by which CAFs contribute to chemoresistance in bladder cancer cells through CXCL14 paracrine signaling." (PMID 40898244, 2025). "The CXCL14/CCR7/STAT3 axis critically mediates cisplatin resistance in bladder cancer through dual modulation of DNA repair and glycolytic metabolism." (PMID 40898244, 2025). "Our results demonstrated that the CXCL14/CCR7/STAT3 axis significantly promotes the glycolytic shift in bladder cancer cells by upregulating the expression of HK2 and LDHA, two key glycolytic enzymes." (PMID 40898244, 2025). "Collectively, our results suggest that CAF-derived CXCL14 targets CCR7 in bladder cancer cells, enhancing ERCC4 transcription through JAK2/STAT3 activation and subsequently binding to the ERCC4 promoter region." (PMID 40898244, 2025). "In combination with previous findings that CXCL14 overexpression is consistent with chemoresistance in bladder cancer patients, we classified abnormal CXCL14 expressing CAFs as differentiated iCAFs or undifferentiated naïve CAFs." (PMID 40898244, 2025). "While little is known about its role in bladder cancer, we observed prevalent expression of CXCL14 in bladder tissues, particularly within normal bladder epithelial cells." (PMID 40898244, 2025). "We used recombinant human CXCL14 (rhCXCL14) to simulate the effect of exogenous CXCL14 on bladder cancer cells." (PMID 40898244, 2025). "Mechanistically, CAF-secreted CXCL14 engaged CCR7 on bladder cancer cells, triggering STAT3 phosphorylation and consequently upregulating the DNA repair gene ERCC4 to promote cisplatin resistance." (PMID 40898244, 2025). "In our study, we observed that CXCL14 expression was significantly elevated in the stroma of bladder cancer tissues compared with adjacent tissues, with a more pronounced increase in cisplatin-resistant tissues." (PMID 40898244, 2025). "In our study, we observed transcriptional upregulation of ERCC4 in CXCL14-induced chemoresistant bladder cancer cells." (PMID 40898244, 2025). "Given the complexity and bidirectionality of signaling interactions within the TME, we further explored whether CXCL14-induced chemoresistant bladder cancer cells contribute to fibroblast activation." (PMID 40898244, 2025). "The analysis revealed that CXCL14 is functionally enriched not only in the"bladder cancer"pathway but also in several cell cycle and DNA damage repair-related pathways, including"base excision repair,""mismatch repair,""nucleotide excision repair,"and"homologous recombination"." (PMID 40898244, 2025). "Nevertheless, the role of CXCL14 in bladder cancer remains to be fully elucidated." (PMID 40898244, 2025). "We then treated bladder cancer cells with CM from different groups, and immunofluorescence staining of γH2AX revealed decreased DNA damage in T24 and UM-UC-3 cells incubated with CAFs/CM, which lost their protective role after CXCL14 expression was modulated." (PMID 40898244, 2025). "In bladder cancer, CXCL14 naturally plays a protective effect, supporting earlier findings." (PMID 38172584, 2024). "We found that the transcription levels of CCL20 and CXCL14 in T24 and TCCSUP cells were significantly increased in the cisplatin treatment groups, and the correlation analysis showed that CCL20 and CXCL14 were significantly correlated with the cGAS-STING signal in the TCGA bladder cancer cohort." (PMID 36230972, 2022).
bladder cancer (continued). "To further confirm the paracrine role of CXCL14 from CAFs in chemoresistance induction in bladder cancer cells, and to explore whether other signaling mechanisms, such as extracellular vesicles or direct contact, could exert similar effects, we cocultured T24 cells with shNC/shCXCL14 CAFs for 24 h." (PMID 40898244, 2025). "Additionally, for the first time, we found that exogenous CXCL14 from CAFs could enhance the NER response of bladder cancer cells by upregulating ERCC4 expression." (PMID 40898244, 2025). "To investigate whether STAT3 binds to the promoter region of ERCC4 and how CXCL14 enhances its expression in bladder cancer cells, we overexpressed STAT3 in 293 T cells as an external validation and modulated STAT3 phosphorylation in T24 cells with rhCXCL14 or rhCXCL14 combined with STAT3i." (PMID 40898244, 2025). "Taken together, our results suggest that disrupting the CXCL14/CCR7/STAT3 signaling axis, both in vitro and in vivo, enhances DNA damage and increases cisplatin sensitivity in bladder cancer." (PMID 40898244, 2025). "Specifically, CXCL14 activates the CCR7/JAK2/STAT3 axis, leading to the upregulation of ERCC4 transcription, which promotes DNA damage repair in bladder cancer cells, thereby facilitating the development of chemoresistance." (PMID 40898244, 2025). "To explore the role of CXCL14 in the development of chemoresistance in bladder cancer, we performed GSEA using RNA-seq data from 414 bladder cancer patients in the TCGA database." (PMID 40898244, 2025). "We specifically focused on the overexpression and secretion of CXCL14 by CAFs, revealing its role in mediating NER responses in bladder cancer cells, which ultimately facilitates the development of chemoresistance." (PMID 40898244, 2025). "Additionally, the interaction between CXCL14 and CCR7 in bladder cancer cells was further validated by fluorescence confocal microscopy." (PMID 40898244, 2025). "Western blot analysis revealed that deficient expression of CXCL14 in CAFs failed to increase the expression of ERCC4 and inhibited DNA damage-induced apoptosis in bladder cancer cells." (PMID 40898244, 2025). "To investigate the impact of exogenous CXCL14 on the chemoresistance of bladder cancer, we collected and cultured patient-derived organoids (PDOs) from a bladder cancer patient who underwent radical cystectomy without prior therapy to assess the clinical relevance of our findings." (PMID 40898244, 2025).